DUSP26 (dual specificity phosphatase 26)
Description:
Inactivates MAPK1 and MAPK3 which leads to dephosphorylation of heat shock factor protein 4 and a reduction in its DNA-binding activity. Inhibits MAP kinase p38 by dephosphorylating it and inhibits p38-mediated apoptosis in anaplastic thyroid cancer cells. Can also induce activation of MAP kinase p38 and c-Jun N-terminal kinase (JNK).
Synonyms: DSP-4; LDP-4; MKP-8; DUSP24; LDP4; MKP8; NATA1; SKRP3; MGC1136; NEAP
Tractability: PROTAC: a small molecule that binds it is known.
Target class: Phosphatase; Serine/threonine/tyrosine protein phosphatase; Enzyme; Protein Phosphatase
Gene: Protein-coding gene on chromosome 8 (33,591,330 to 33,600,176, reverse strand). Ensembl gene ENSG00000133878.
Subcellular location: Cytoplasm; Nucleus; Golgi apparatus
Subcellular location (Human Protein Atlas): Nucleoplasm
Gene Ontology:
Molecular function: phosphoprotein phosphatase activity; protein binding; protein tyrosine/serine/threonine phosphatase activity; RNA polymerase II-specific DNA-binding transcription factor binding; MAP kinase phosphatase activity; phosphatase activity; protein serine/threonine phosphatase activity; protein tyrosine phosphatase activity
Biological process: negative regulation of ERK1 and ERK2 cascade; negative regulation of transcription by RNA polymerase II; positive regulation of cell adhesion; protein dephosphorylation; negative regulation of MAPK cascade
Cellular component: cytoplasm; extracellular exosome; Golgi apparatus; nucleoplasm; nucleus
Genetic constraint (gnomAD): Loss-of-function variants: 13 observed, 21.16 expected, observed/expected ratio (o/e) 0.61, 90% interval 0.4 to 0.98. The upper end of that interval is the gene's LOEUF score, 0.98, which puts it in group 4 of 6, group 1 being the genes least tolerant of losing a copy. Missense variants: 230 observed, 305.73 expected, observed/expected ratio (o/e) 0.75, 90% interval 0.68 to 0.84. Synonymous variants: 120 observed, 125.02 expected, observed/expected ratio (o/e) 0.96, 90% interval 0.83 to 1.12.
Homologues: Orthologues: chimpanzee DUSP26 (100% identical), macaque DUSP26 (99% identical), dog DUSP26 (98% identical), rat Dusp26 (98% identical), guinea pig DUSP26 (97% identical), mouse Dusp26 (97% identical), pig DUSP26 (94% identical), zebrafish DUSP26 (61% identical), tropical clawed frog dusp26 (58% identical). Paralogues in human: DUSP13A (48% identical), DUSP29 (43% identical), DUSP13B (42% identical), DUSP3 (35% identical), STYXL2 (33% identical), DUSP18 (30% identical), DUSP4 (29% identical), SSH3 (29% identical), DUSP1 (28% identical), DUSP14 (28% identical), DUSP5 (28% identical), DUSP2 (27% identical), and 19 more.
Diseases named in the same sentence as DUSP26 in open-access papers:
DUSP26 is named in the same sentence as 48 diseases in open-access papers, as found by Europe PMC text mining. Sharing a sentence is not in itself a finding about the gene and the disease. The quoted sentences say what the papers report.
neuroblastoma (9 papers, 2011 to 2022). Neuroblastoma (NB) is the most common solid, extracranial childhood tumor. "For example, DUSP26 is implicated in cancer, with potential roles in neuroblastoma, anaplastic thyroid cancer, glioblastoma and breast cancer, among others." (PMID 33466673, 2021). "In IMR32 neuroblastoma cells, DUSP26 co-immunoprecipitated with N-cadherin, β-catenin and the KIF3 motor complex via the KIF3a subunit." (PMID 33466673, 2021). "Because DUSP26 is a novel therapeutic target for the treatment of neuroblastomas and pediatric malignancies, the crystal structure of DUSP26-N (C152S) will be useful for the rational design of novel DUSP26-targeting anticancer therapeutics." (PMID 27583453, 2016). "Specifically, p38 signaling was downregulated in neuroblastoma via inhibition of dual-specificity protein phosphatase 26 (DUSP26), mitogen induced ERK1/2 activation was downregulated in breast cancer cells, and JNK activity was downregulated in CD8+ T cells in murine encephalomyelitis." (PMID 35763355, 2022). "In particular, DUSP26 expression is severely unregulated in neuroblastoma cells." (PMID 27583453, 2016). "Thus, DUSP26 has been suggested as a novel therapeutic target for the treatment of neuroblastomas that are insensitive to chemotherapy and related pediatric malignancies." (PMID 27583453, 2016). "In addition, in human neuroblastoma, the dual-specificity phosphatase 26 (DUSP26) is overexpressed." (PMID 24212658, 2011). "Therefore, the negative control exerted by DUSP26 on HSF4, altogether with the inverse correlation in the expression of these two proteins in neuroblastoma, may contribute to repress HSF4 activity in neuroblastoma and its potential crosstalk with HSF1." (PMID 24212658, 2011).
glioblastoma (6 papers, 2016 to 2022). The most malignant astrocytic tumor (WHO grade IV). "Supporting the potential suppressive role, DUSP26 overexpression in E98 glioblastoma cells caused a reduction in cell proliferation accompanied by a reduction in spheroid outgrowth." (PMID 33466673, 2021). "A case in point is glioblastoma, where DUSP26 mRNA expression is reduced in tumour specimens and inversely correlates with the histological grade of the tumour." (PMID 33466673, 2021). "Relationships between DUSP26 expression and clinicopathological characteristics in 180 glioblastoma (GBM) cases." (PMID 33718185, 2021). "The role of DUSP26 in the development and prognosis of high-grade gliomas (HGGs) and primary glioblastoma (GBM) has remained unclear and was the focus of this study." (PMID 33718185, 2021). "In glioblastoma, DUSP26 mRNA expression is downregulated and plays a role in intracellular transport and cell-cell adhesion." (PMID 29682206, 2018). "To also monitor potential DUSP26 or PTPRT effects on glioblastoma cell migration, we turned to a previously established spheroid outgrowth assay." (PMID 27586084, 2016). "Other investigators also reported on down-regulated DUSP26 levels in glioblastoma and Tanuma and colleagues additionally provided evidence that DUSP26 facilitates catenin/cadherin delivery to cell-cell junction sites, hence cell-cell adhesiveness." (PMID 27586084, 2016). "Low-level DUSP26 stainings were observed in 21 and 12 % of lower grade and glioblastoma samples, respectively, in concordance with our qPCR findings." (PMID 27586084, 2016). "For DUSP26, PTEN, PTPRM and PTPRT, lower expression levels correlated with poor prognosis, and overexpression of DUSP26 or PTPRT in E98 glioblastoma cells reduced tumorigenicity." (PMID 27586084, 2016). "Collectively, this indicates that DUSP26 acts as an oncogene, and contrasts with our observation of low DUSP26 levels in glioblastomas in comparison with lower grade glioma samples and normal brain tissue." (PMID 27586084, 2016). "DUSP26 is negatively correlated with GPX8, and low DUSP26 expression could lead to malignant behavior in glioblastoma cells by deregulating MAPK and Akt signaling pathway." (PMID 36052280, 2022). "Although overexpression of DUSP26 in glioblastoma cells suppresses cell proliferation, the physiological role of DUSP26 remains unclear." (PMID 33466673, 2021). "A tumour-suppressive role of DUSP26 is also seen in glioblastoma." (PMID 33466673, 2021). "Importantly, we found that DUSP26 overexpression in E98 glioblastoma cells resulted in decreased growth and motility." (PMID 27586084, 2016). "Moreover, the mRNA level of DUSP26 was downregulated in human glioblastoma samples." (PMID 33718185, 2021). "Importantly, overexpression of the two PTPs that showed the largest expression difference in our qPCR and in silico analyses, DUSP26 and PTPRT, resulted in reduced glioblastoma cell proliferation and migration, supportive of a tumor suppressive role." (PMID 27586084, 2016). "DUSP26 and PTPRT thus impinge on both growth and motility of glioblastoma cells." (PMID 27586084, 2016). "Notably, seven PTP genes (DUSP26, MTMR4, PTEN, PTPRM, PTPRN2, PTPRT and PTPRZ1) were differentially expressed between grade II-III gliomas and (grade IV) glioblastomas." (PMID 27586084, 2016). "Also within the individual histological types (oligodendroglioma (grade II-III), astrocytoma (grade II-III) and glioblastoma (grade IV)) we observed expression-dependent survival probabilities for DUSP26 and PTPRT (data not shown)." (PMID 27586084, 2016).
breast carcinoma (5 papers, 2014 to 2023). "It would be intriguing to see whether the LOH of 8p12 breast cancer specimens correlates with an increased FADD-Pi which would support the functional effect of loss of DUSP26 in breast cancer." (PMID 33466673, 2021). "In ANA-positive cases, time to breast cancer diagnosis decreased in association with PGM3 intensity and were increased for DUSP26." (PMID 38002248, 2023). "Loss of AK2 expression is associated with rapid cell proliferation and often found in breast cancers, providing a molecular basis for the role of AK2/DUSP26 complex as a potent regulator of tumour growth." (PMID 24548998, 2014). "Moreover, all of the five cancers (100%) showing high level of p-FADD signal ablated the expression of both AK2 and DUSP26, underscoring a strong cross-talk for an inverse correlation between AK2/DUSP26 expression and p-FADD in the human breast cancers." (PMID 24548998, 2014). "Dysregulation of this AK2/DUSP26/FADD signalling pathway does not have to be limited to breast cancer." (PMID 24548998, 2014).
anaplastic thyroid cancer (2 papers, 2016 to 2021). "Furthermore, DUSP26 amplification has been found in thyroid cancer, and DUSP26 knockdown impeded growth of anaplastic thyroid cancer cells." (PMID 27586084, 2016). "The 8p12 region was amplified in anaplastic thyroid cancer (ATC) primary tumours and cell lines and DUSP26 mRNA was upregulated in cases exhibiting copy number increases, suggesting a potential role of DUSP26 in promoting tumour cell growth." (PMID 33466673, 2021).
glioma (2 papers, 2016 to 2021). A benign or malignant brain and spinal cord tumor that arises from glial cells (astrocytes, oligodendrocytes, ependymal cells). "As high DUSP26 expression associates with low histologic stage and better prognosis in glioma patients, we next investigated the anti-tumor effect of DUSP26 via overexpression of DUSP26 in the U251 and U87 GBM cells." (PMID 33718185, 2021). "Ultimately, we have characterized tumor suppressor role of DUSP26 and highlights potential application of DUSP26 expression profiling as a prognostic marker in glioma patients." (PMID 33718185, 2021). "Stratification of glioma patients based on DUSP26 expression level showed an inverse correlation between DUSP26 expression and patient survival." (PMID 33718185, 2021). "By correlative analysis of DUSP26 expression with patient survival, we have verified that DUSP26 expression can be predictive of histology stage and survival outcome in human glioma patients." (PMID 33718185, 2021). "In summary, high DUSP26 expression correlates with the low histologic stages of glioma, while DUSP26 is down-regulated or suppressed in HGGs, which include GBM." (PMID 33718185, 2021). "Analyses using available online data sets and tissue microarray showed that DUSP26 is down-regulated in high-grade gliomas and GBM as compared to normal brain." (PMID 33718185, 2021). "As the advanced histology stage historically predicts poor survival in glioma patients, we asked if there is any relationship between DUSP26 expression and patient survival." (PMID 33718185, 2021). "As high DUSP26 expression predicts better survival and lower histology stage in human glioma patients, we next checked the effects of DUSP26 overexpression on proliferation and migration of GBM cells, where basal levels of DUSP26 are low." (PMID 33718185, 2021). "With a tight correlation between DUSP26 expression levels and patient survival, DUSP26 can serve as a prognostic marker in glioma patients." (PMID 33718185, 2021). "In summary, the high DUSP26 expression is associated with better survival in glioma patients regardless of their age, sex, and treatment history." (PMID 33718185, 2021). "Interestingly, the low DUSP26 group had only 39 cases (43.3%) of low grade (stage I ̃II) gliomas, while 51 cases (56.7%) were HGGs (stage III ̃IV)." (PMID 33718185, 2021). "It is becoming increasingly clear that diffuse glioma cells form functional networks via cell-cell contacts and in such a context DUSP26 protein may indeed have tumor suppressive activity." (PMID 27586084, 2016). "Similarly, assays to reliably detect DUSP26 or its upstream regulatory events may help delineate the applicability of DUSP26 as a prognostic biomarker for glioma patients." (PMID 33718185, 2021). "To address this hypothesis, we have analyzed the biologic effects of DUSP26 overexpression in GBM cells and have retrospectively analyzed the prognostic role of DUSP26 using a tissue microarray developed from glioma patients with known histology and characteristics." (PMID 33718185, 2021). "Together with PTPs that impinge upon cellular contacts (DUSP26, PTPRZ1) and phospholipid signaling (MTMR4, PTEN and PTPRN2) they provide novel cues to explore and design glioma treatment options." (PMID 27586084, 2016). "DUSP26 and PTPRT are the most down-regulated PTPs in gliomas with highest grade malignancy and both show a pronounced correlation with survival probability." (PMID 27586084, 2016). "We additionally identified PTPRT, DUSP26, PTPRN2 and MTMR4 in our screen for glioma-relevant PTPs." (PMID 27586084, 2016). "As DUSP26 is down-regulated in GBM but not in low-grade gliomas, we next checked whether the expression of DUSP26 correlates with the progression of human gliomas." (PMID 33718185, 2021).
thyroid cancer (2 papers, 2016 to 2018). "In thyroid cancer, for example, DUSP26 is amplified and promotes cell growth by inhibiting the p38 MAPK activity." (PMID 29682206, 2018).
breast tumour (1 paper, 2021). "In another study, a decrease in DUSP26 mRNA expression was observed in 8 of 14 primary breast tumour samples." (PMID 33466673, 2021). "One study analysed 234 breast tumour samples and identified an increase and decrease of DUSP26 gene copy number in 16% and 10% of cases, respectively." (PMID 33466673, 2021).
calcific aortic valve disease (1 paper, 2023). "DUSP26 is up-regulated in calcific aortic valve disease (CAVD), and its silencing can reduce aortic valve calcification in mice model." (PMID 37240861, 2023).
embryonal cancers (1 paper, 2019). A non-seminomatous malignant germ cell tumor characterized by the presence of large germ cells with abundant cytoplasm resembling epithelial cells, geographic necrosis, high mitotic activity, and pseudoglandular and pseudopapillary structures formation. "DUSP26 (MKP8) was originally identified as a DUSP mainly expressed in embryonal cancers and displaying substrate specificity towards p38 in cells." (PMID 30866462, 2019).
Hepatic steatosis (1 paper, 2022). Steatosis is a term used to denote lipid accumulation within hepatocytes. "According to our current findings, previous studies, and the characteristic of DUSPs family, we demonstrated that the dephosphorylating capacity of DUSPs family members (DUSP22, DUSP3, DUSP9, DUSP12, DUSP14, DUSP26, etc) might be indispensable for its protective role against hepatic steatosis." (PMID 36209205, 2022).
Insulin resistance (1 paper, 2021). Increased resistance towards insulin, that is, diminished effectiveness of insulin in reducing blood glucose levels. "The rescue effect of TAK1 is yet to be confirmed in transgenic mice, but results suggest that TAK1-activation of NF-kB drives insulin resistance and lipid accumulation and is at least partially controlled by DUSP26." (PMID 33466673, 2021). "DUSP26 inhibited insulin resistance as HFD-fed DUSP26-KO mice displayed higher insulin plasma levels and lower glucose tolerance." (PMID 33466673, 2021).
liver fibrosis (1 paper, 2022). "Among all these analyzed DUSPs, DUSP3, DUSP8, DUSP12, DUSP14, DUSP16, DUSP22, and DUSP26 were significantly decreased in the liver of NASH patients with obvious hepatocyte ballooning, severe inflammatory infiltrate, and pattern of liver fibrosis compared with the normal individuals." (PMID 36209205, 2022).
Oesophageal cancer (1 paper, 2024). "DUSP5 was the most epimutated DUSP in Stomach (17%), Pancreas (2%) and equal to DUSP26 in Oesophageal cancer (9%)." (PMID 38475971, 2024).
osteoarthritis (1 paper, 2026). A noninflammatory degenerative joint disease occurring chiefly in older persons, characterized by degeneration of the articular cartilage, hypertrophy of bone at the margins and changes in the synovial membrane. "Collectively, the findings of the present study underscore DUSP26 as a promising therapeutic target for DDH‐associated osteoarthritis, offering novel mechanistic insights and laying the groundwork for the development of targeted interventions to mitigate secondary joint degeneration." (PMID 41789628, 2026).
ovarian carcinoma (1 paper, 2018). A malignant neoplasm originating from the surface ovarian epithelium. "Furthermore, DUSP26 mRNA expression was enhanced by treatment of ovarian cancer cell lines with 5-aza-2-deoxycytidine (demethylation) and trichostatin A (HDAC inhibitor)." (PMID 29682206, 2018).
pancreatic adenocarcinoma (1 paper, 2023). "In TGF-induced pancreatic adenocarcinoma (PANC-1) cells, silencing of DUSP26 expression by siRNA markedly suppressed the effect of TGFβ1 on E-cadherin and mesenchymal genes in the cells." (PMID 37476896, 2023).
sarcoma (1 paper, 2019). A usually aggressive malignant neoplasm of the soft tissue or bone. "Among the genes that are downregulated in sarcoma in all three species, there are three known tumor suppressors: TP63, EPHA1, and DUSP26 (which may alternately function as an oncogene depending on the cancer context)." (PMID 30947707, 2019).